MYOF (myoferlin)
Diseases named in the same sentence as MYOF in open-access papers (continued):
Sharing a sentence is not in itself a finding about the gene and the disease.
MYOF also shares sentences with these, for which no sentence is quoted: adenocarcinoma (2 papers); dysferlinopathies (2); Limb-Girdle Muscular Dystrophy type-2B (2); amelanotic melanoma (1); amyotrophic lateral sclerosis (1); auditory neuropathy (1); bladder urothelial carcinoma (1); breast adenocarcinoma (1); Corneal astigmatism (1); deafness (1); fibrosis (1); gastrointestinal disease (1); glaucoma (1); glioblastoma (1); glioma (1); heart failure (1); in situ breast carcinoma (1); lung adenocarcinoma (1); lymphoma (1); metastatic cancer (1); metastatic tumors (1); movement disorder (1); muscular disorders (1); myopia (1); neurodegenerative disease (1); non-small cell lung adenocarcinoma (1); Obesity (1); ovarian carcinoma (1); Pancreas (1); Parkinson disease (1).
A further 7 diseases each share a sentence with MYOF in 1 paper.